ENSG00000266302 (novel transcript)
Gene: Protein-coding gene on chromosome 17 (16,690,261 to 16,804,453, forward strand). Ensembl gene ENSG00000266302.
Genetic constraint (gnomAD): Missense variants: 563 observed, 998.14 expected, observed/expected ratio (o/e) 0.56, 90% interval 0.52 to 0.61. Synonymous variants: 217 observed, 341.88 expected, observed/expected ratio (o/e) 0.63, 90% interval 0.57 to 0.71.